ICAM1 (intercellular adhesion molecule 1)
Diseases named in the same sentence as ICAM1 in open-access papers (continued):
Sharing a sentence is not in itself a finding about the gene and the disease.
ovarian carcinoma (continued). "The ICAM-1/CD18 axis in TME can form a positive autocrine feedback loop in ovarian cancer models, thereby promoting tumor cell proliferation, migration, spheroid formation, and peritoneal implantation." (PMID 36497444, 2022). "On the other hand, it has been proven that ICAM-1 suppresses colon and ovarian cancer metastasis and growth." (PMID 34680113, 2021). "Pharmacological blockade of EGFR or neutralizing antibody for ICAM-1 in TAMs blunted spheroid formation and ovarian cancer progression in mouse models." (PMID 33194645, 2020). "Both P-selection and ICAM-1 are associated with the A1 allele of the ABO blood group, which was shown to be associated with increased ovarian cancer risk by OCAC." (PMID 28448592, 2017). "When binding to ICAM-1 was neutralized with antibodies, spheroid formation and ovarian cancer progression were impaired." (PMID 29099772, 2017). "The induced ICAM-1 protein is responsible for the survival of ovarian cancer cells by inhibiting apoptosis under severe hypoxic conditions that trigger ER stress." (PMID 27589734, 2016). "By contrast, a recent study using ovarian cancer cells showed that the ICAM1 gene, which encodes intercellular adhesion molecule-1 (ICAM-1), is synergistically activated when cells are exposed to both LCFA starvation and hypoxic conditions." (PMID 27589734, 2016). "The results showed that similar to the stimulation of ovarian cancer organoids, the proportions of CD11b+, CD66b+, and ICAM-1+ neutrophils in each case of neutrophils were significantly increased after MUC16 treatment for 24 h, while the proportions of CXCR4+ neutrophils were decreased slightly." (PMID 37644468, 2023). "Moreover, pioneering studies employing retroviral transduction of Zinc-finger proteins engineered with TET-2-CD have shown reactivation of candidate TSGs, such as C13ORF18 and TFPI2 in cervical cancer cells, and ICAM-1 in ovarian cancer cells." (PMID 37120619, 2023). "The elevated expression of ICAM-1 in freshly isolated ovarian cancer cells suggests that ICAM-1 expression may promote the malignant progression of ovarian cancer." (PMID 35630004, 2022). "Our understanding of the role of ICAM-1 in ovarian cancer development remains limited." (PMID 35630004, 2022). "In a separate ovarian cancer study anti-ICAM-1 blocking antibodies only partly blocked CD8+ T cell infiltration, suggesting that additional molecules like VCAM-1 may mediate CD8+ T cell extravasation as well." (PMID 33262763, 2020). "However, it has also been reported that ICAM-1 is expressed at low levels in some carcinomas, even in ovarian carcinoma." (PMID 31312656, 2019). "However, this study also showed that induction of ICAM1 leads to reduced CDDP sensitivity in ovarian cancer cells." (PMID 29849953, 2018). "Thus, this study aimed to investigate the role of HLA-DP rs3077 (A/G), HLA-DQ rs3920 (A/G), and ICAM-1 rs1437 (C/T) SNPs in diagnosis and/or prognosis of ovarian cancer." (PMID 27252704, 2016). "HLA-DP rs3077, HLA-DQ rs3920, and ICAM-1 rs1437 SNPs could help in the diagnosis and prognosis of ovarian cancer." (PMID 27252704, 2016). "Thus in our samples, we have analyzed HLA-DP rs3077 (A/G), HLA-DQ rs3920 (A/G), and ICAM-1 rs281437 (C/T) SNPs in benign, borderline, malignant ovarian tumors’ patients, and normal controls." (PMID 27252704, 2016). "ICAM-1 rs1437 CC genotype was expressed in 10, 0, 70, and 0% of benign, borderline, malignant ovarian tumors, and healthy volunteers, respectively, while CT genotype was expressed in 35, 80, 25, and 40% of benign, borderline, malignant ovarian tumors, and healthy volunteers, respectively." (PMID 27252704, 2016). "Furthermore, our data contradict earlier reports showing that ICAM1 suppresses ovarian cancer progression." (PMID 25879517, 2015). "Thus, we next examined whether ICAM1 confers a survival advantage to ovarian cancer cells under SSH." (PMID 25879517, 2015).
ovarian carcinoma (continued). "In ovarian cancer cell lines SKOV-3 and OVCAR-3, Ex-4 induces apoptosis by modulating NF-κB downstream targets, including matrix metalloproteinase-9 (MMP-9), intercellular adhesion molecule-1(ICAM-1), BAX, Bcl-2, and cyclin D." (PMID 40140925, 2025). "Ovarian cancer stem cells (CSCs) were found to exhibit lower surface expression of MHC-class I, intercellular adhesion molecule 1 (ICAM-1 or CD54), and programmed death-ligand 1 (PD-L1) receptors, while exhibiting higher expression of CD44." (PMID 41375063, 2025). "We did not observe upregulation of prototypical endothelial cell markers (CD31, CD34, VE-cadherin, Icam1, and Vcam1) upon ectopic expression of FOXC2 in mouse ovarian cancer cells." (PMID 36230774, 2022). "It is very plausible that this effect was associated with the higher secretion levels of several agents known to support ovarian cancer cell progression by these cells, such as CCL2, CXCL8, CXCL12, ICAM-1, IL-6, HGF, PAI-1, uPA, TGF-β1, and VEGF." (PMID 31086083, 2019). "The second genetic vaccine tested in ovarian cancer (PANVAC-C + PANVAC-V) was a poxviral vaccine, in which the CEA-MUC1-TRICOM (B7.1, ICAM-1, LFA-3) was engineered into vaccinia (PANVAC-V) as a prime and fowlpox (PANVAC-C) as a booster vaccination." (PMID 29662489, 2018). "These alterations were shown to facilitate the adhesion of ovarian cancer cells mainly via (i) exposure of submesothelial ECM, where cancer cells preferably adhere, and via (ii) upregulated expression of ICAM-1/VCAM-1, HA, and FN1, providing integrin- and CD44-mediated ovarian cancer cell adhesion." (PMID 33270665, 2020). "The second group of viral genetic vaccines tested in ovarian cancer (PANVAC-C + PANVAC-V) involved a poxviral vaccine that is genetically engineered with CEA-MUC1-TRICOM (B7.1, ICAM-1, LFA-3) into fowlpox (PANVAC-C) as a booster and vaccinia (PANVAC-V) as a prime vaccination." (PMID 29662489, 2018). "Other conceivable molecules for targeting ovarian cancer cells include follicle-stimulating hormone receptor (FSHR), intercellular adhesion molecule 1 (ICAM-1), Müllerian inhibiting substance type II receptor (MISIIR), and human epidermal growth factor receptor 2 (HER2)." (PMID 24354786, 2013). "Inflammatory cytokines in ovarian cancer cells, including tumor necrosis factor-α (TNF-α) and interleukin-1 (IL-1), promote malignant progression—such as tumor cell migration and invasion—by upregulating the expression of vascular cell adhesion molecule-1 (VCAM-1) and ICAM-1." (PMID 40140925, 2025). "In this study, we showed that EVs from ovarian cancer cells upregulated genes related to the inflammatory response, including immune cell–attracting cytokines (CCL2, CCL3/L1, CCL15, CCL18, and CCL20), interleukins (IL1B and IL32), and cell–cell adhesion transcripts (VCAM1 and ICAM1)." (PMID 40689422, 2025). "In mouse models of ovarian cancer, overexpression of the endothelin B receptor (ETBR) negatively regulates ICAM1 expression on the endothelium and limits the ability of T cells to access the tumor, such that inhibition of ETBR improves T cell infiltration in an ICAM1-dependent manner." (PMID 31497019, 2019). "In addition, it was recently reported that upregulation of ICAM1 suppresses growth of ovarian cancer cells in the absence of immune cells." (PMID 29849953, 2018). "Some studies have shown that ICAM1 expression impairs progression of non-CCC ovarian cancers." (PMID 25879517, 2015). "Furthermore, in human ovarian cancer cells (OV17-1) a neutralizing antibody blocking ICAM-1 ameliorated the enhanced CTL lysis seen with Ang1 and Ang2 inhibitors, demonstrating that ICAM-1 was mechanistically involved in the increase in antigen-specific T-cell lysis." (PMID 26579226, 2015).
ovarian carcinoma (continued). "Other potential target molecules for targeting ovarian cancer cells might include follicle-stimulating hormone receptor (FSHR), intercellular adhesion molecule 1 (ICAM-1), Müllerian inhibiting substance type II receptor (MISIIR), or human epidermal growth factor receptor 2 (HER2)." (PMID 22509395, 2012).
metabolic syndrome (46 papers, 2007 to 2026). A cluster of metabolic risk factors for CARDIOVASCULAR DISEASES and TYPE 2 DIABETES MELLITUS. "The correlation of decreased ICAM-1 with triglycerides and p-selectin with hip circumference is in accord with their relationship with metabolic syndrome and their reduction that reflected the weight loss." (PMID 31001199, 2019). "ICAM1 is an important inflammatory marker, which was associated with metabolic syndrome by multiple linear regression models." (PMID 28316372, 2017). "Liver enzymes, C-reactive protein (CRP), interleukin-6, soluble intercellular adhesion molecule-1 (sICAM-1), adipokines, and parameters related to metabolic syndrome (MetS) were all measured." (PMID 33665176, 2021). "Here we report that the practice of moderate acute exercise (60–70% of HRmax) for 30 min by metabolic syndrome patients increased TNFα and ICAM1 concentrations but maintained pre-exercise concentrations of IL6 at 30 min post-exercise." (PMID 32646062, 2020). "An altered expression of ILs, TNFα, ICAM1 genes and of their respective receptors in adipose tissue as well as in PBMC has been implicated in the higher risk of suffering metabolic syndrome and cardiovascular disease." (PMID 20465828, 2010). "Cardiovascular risk factors such as high glucose and dyslipidemia activate the vascular endothelium to secrete inflammatory chemokines (MCP1 and IL8) and adhesion molecules (ICAM1, VCAM1, and E-Selectin), which leads to monocyte binding to the vasculature and the subsequent vascular inflammation." (PMID 37627522, 2023). "Markers of chronic inflammation (ICAM-1, TIMP) are elevated in FS patients, and pro-inflammatory lipoproteins are significant risk factors for FS, similar to patients with cardiovascular disease or metabolic syndrome." (PMID 33205235, 2020). "Moreover, a meta-analysis revealed that EPA supplementation decreased the circulating levels of adhesion molecules, including soluble ICAM-1 and soluble forms of vascular cell adhesion molecule (sVCAM)-1, both in participants with dyslipidemia and in healthy controls." (PMID 33187281, 2020). "ICAM-1 is upregulated by several stimuli, including VEGF, poly (ADP-ribose) polymerase activation, oxidative stress, and dyslipidemia." (PMID 35126785, 2022). "A mediation analysis implied that, among the metabolic syndrome components, body mass index was directly related to elevated high-sensitivity C-reactive protein levels and indirectly via HDL-c to elevated intercellular adhesion molecule 1 levels." (PMID 33677859, 2021). "Acute exercise increased the plasma concentration of TNFα, intercellular adhesion molecule ICAM1, PGE1, PGE2 and the newly detected 16-hydroxypalmitic acid (16-HPAL) in metabolic syndrome patients." (PMID 32646062, 2020). "In metabolic syndrome, bio-enhanced curcumin formulations have consistently improved lipid profiles but have shown variable effects on endothelial biomarkers such as VCAM-1, intercellular adhesion molecule-1 (ICAM-1), and flow-mediated dilation." (PMID 41302164, 2025). "Irisin inhibits the levels of cell adhesion molecules (CAMs), such as intercellular adhesion molecule 1 (ICAM-1), vascular cell adhesion protein 1 (VCAM-1), and E-selectin, which are elevated by dyslipidemia and reduces leukocyte and monocyte adhesion to the arterial wall surface." (PMID 38029393, 2023). "Given the high prevalence of major depression and MetS in the population, we hypothesized that depression symptoms influence metabolic syndrome or its components through the action of inflammatory biomarkers such as hs-CRP and ICAM-1." (PMID 34065158, 2021). "In contrast to VCAM-1, changes in ICAM-1 surface expression did not correlate with any clinical indicators of dyslipidemia." (PMID 31209255, 2019).
metabolic syndrome (continued). "Overall, the current meta-analysis demonstrated that vitamin D supplementation to patients with metabolic syndrome and related disorders resulted in an improvement in vWF, but did not affect ICAM-1, VCAM-1, E-selectin and endothelin levels." (PMID 30519274, 2018). "We investigate adiponectin ICAM-1, VCAM-1, and metabolic syndrome (MetS) in obese adolescents." (PMID 37822716, 2023).
Cerebral ischemia (45 papers, 2009 to 2025). Restriction of arterial blood supply to the brain associated with insufficient oxygenation to support the metabolic requirements of the tissue. "An association between VEGF and ICAM-1 and cerebral ischemia has been described." (PMID 41149263, 2025). "SHD can significantly attenuate swelling, degeneration, and necrosis of neural cell, as well as infiltration of inflammatory cells caused by cerebral ischemia, and can significantly reduce the expression of interleukin-1β (IL-1β) and intercellular adhesion molecule 1 (ICAM-1)." (PMID 37123364, 2023). "ICAM‐1 is an important endothelial‐associated transmembrane protein that is involved in neutrophil adhesion, and its expression increases dramatically after cerebral ischemia." (PMID 34156153, 2021). "Activated endothelial cells also release E-selectin, vascular cell adhesion molecule 1 (VCAM-1), and intercellular adhesion molecule 1 (ICAM-1), which further support leukocyte binding and migration after cerebral ischemia." (PMID 41245147, 2025). "Activation of NF-κB induces the production of pro-inflammatory cytokines (IL-4, IL-10, IL-13, TGF-β) and adhesion molecules (IL-6, IL-1β and ICAM-1), thus intensifying tissue injury in cerebral ischemia-reperfusion." (PMID 40656619, 2025). "The genes CCL2, ICAM1, and JUN were identified as being associated with neurological disorders such as brain ischemia and schizophrenia." (PMID 39024368, 2024). "In a cerebral ischemia/reperfusion rat model treated with dauricine, ICAM-1 was proven to be significantly reduced." (PMID 34925018, 2021). "In a cerebral ischemia/reperfusion rat model, dauricine attenuated the inflammatory process by downregulating the expression of ICAM-1, TNF-α, and IL-1β." (PMID 34925018, 2021). "Inhibition or deletion of ICAM-1 has already been shown by various laboratories to be protective after cerebral ischemia; however, so far, it was believed that blocking adhesion results in reduced transmigration." (PMID 35140676, 2021). "Cerebral ischemia activates leukocyte adhesion and initiation of inflammation in the brain and this is mediated by the interaction of leukocytes' β2‐integrins with ICAM‐1 on cerebral endothelial cells." (PMID 33969931, 2021). "Among them, the role of ICAM-1 has been the relatively most researched in the pathophysiology of brain ischemia/reperfusion." (PMID 34868060, 2021). "XQ-1H suppressed neutrophils infiltration and inflammatory mediators, including cerebral ischemia induced intercellular adhesion molecule 1 (ICAM-1) and matrix metalloproteinase-9 (MMP-9), into the ischemic region of the brain." (PMID 31864312, 2019). "NBP induced downregulation of intercellular adhesion molecule 1 and protease-activated receptor 1 in cerebrovascular endothelial cells after cerebral ischemia and reperfusion." (PMID 31595195, 2019). "ICAM‐1 knockout mice show reduced leukocyte adhesion, small infarction, improved cerebral blood flow, and reduced mortality after cerebral ischemia and reperfusion." (PMID 31157518, 2019). "After cerebral ischemia, ICAM-1, ICAM-2, VCAM-1, and PECAM-1 have been shown to contribute to the inflammatory response." (PMID 28115020, 2017). "Western blot analysis revealed that cerebral ischemia significantly increased ICAM-1 expression compared with the sham-operated group (P < 0.05)." (PMID 27782211, 2016). "Persimmon leaf flavonoid isolated from Diospyros kaki L.F (Shi Zhi Ye) exerts anti-inflammatory effects by downregulating ICAM-1 expression in the ischemic area 2 h after cerebral ischemia and 24 h after reperfusion." (PMID 27703487, 2016). "The neuroprotective effects of emodin can be attributed to ICAM-1 downregulation in the ischemic area in the early phase of cerebral ischemia." (PMID 27703487, 2016). "TCMs can effectively attenuate leukocyte infiltration by inhibiting ICAM-1 and activated leukocyte-induced cytokine expression in the ischemic region in the early phase of cerebral ischemia." (PMID 27703487, 2016).